TBX21 (T-box transcription factor 21)
Diseases named in the same sentence as TBX21 in open-access papers (continued):
Sharing a sentence is not in itself a finding about the gene and the disease.
colon carcinoma (3 papers, 2024 to 2025). "TBX21 inhibits the proliferation of colon cancer cells through an ARHGAP29/RSK/GSK3β-dependent mechanism." (PMID 39744435, 2025). "Recent studies have shown that ARHGAP29 is a direct target gene of TBX21, is positively regulated by TBX21, and plays an important role in inhibiting the proliferation and promoting apoptosis of colon cancer cells." (PMID 39744435, 2025).
cutaneous melanoma (3 papers, 2022 to 2025). A primary melanoma arising from atypical melanocytes in the skin. "In lung adenocarcinoma, TBX21 expression enhances tumor cell recognition and clearance by the immune system, while increased TBX21 expression in cutaneous melanoma is associated with a better prognosis." (PMID 36620585, 2022). "Herein, similar to expressions of TBX21 in cutaneous melanoma reported by Zhang, TBX21 was strikingly upregulated in PCa tissues based on RNA-seq, the upregulation of which was verified in tumor tissues from PCa patients and PCa cell lines." (PMID 41573646, 2025).
experimental autoimmune encephalomyelitis (3 papers, 2016 to 2025). An autoimmune demyelinating disease of the central nervous system that is produced experimentally in animals by the injection of homogenized brain or spinal cord in Freund's adjuvant. "In stark contrast, using experimental autoimmune encephalomyelitis, we show that IL-17ACre–mediated deletion of Tbx21 prevents the conversion of Th17 cells to IL-17A/IFN-γ double-producing cells as well as Th1-like IFN-γ+ ex-Th17 cells." (PMID 27183623, 2016).
ulcerative colitis (3 papers, 2015 to 2023). An inflammatory bowel disease involving the mucosal surface of the large intestine and rectum. "A predominance of ILC3 secreting IL-17A accompanied by few IFN-γ-expressing cells was also described in the Tbx21-/-Rag2-/- ulcerative colitis (TRUC mice) disease model." (PMID 25853847, 2015). "In order to determine whether CD90- and CD90low ILC were associated with a T-bet-expressing ILC subset, we analyzed CD90- and CD90low ILC in Tbx21-/- x Rag2-/- non-ulcerative colitis (TRnUC) mice." (PMID 37114052, 2023).
uveitis (3 papers, 2015 to 2020). An inflammatory process affecting a part of or the entire uvea. "In the present study, we noted dynamic methylation changes of Tbx21 and Rorc, the signature transcription factors of Th1 cells and Th17 cells, supporting our finding that the alteration of methylation status of Tbx21 and Rorc is closely associated with the disease progression of uveitis." (PMID 30254507, 2018). "However, to the best of our knowledge, the DNA methylation dynamics of Tbx21, Gata3, Rorc, and Foxp3 during the development of autoimmune disease has not yet been studied and was therefore the subject of our study, whereby we chose uveitis as a disease model." (PMID 30254507, 2018). "Previous studies found the dysregulations of TBX21/GATA3 and Rorc/Foxp3 ratios in uveitis patients with neuro-BD20, suggesting that a dysregulated function of these T cell subsets may lead to immune imbalance, proliferation and activation of pathogenic CD4+ T cells subsequently leading to uveitis." (PMID 25873156, 2015). "FOXP3 and TBX21 were increased in our cases compared to healthy controls, which correlates with data revealing increased expression of these transcription factors in VKH patients during an active uveitis episode." (PMID 33384688, 2020).
allergic disease (2 papers, 2012 to 2023). An immune response that occurs following re-exposure to an innocuous antigen, and that requires the presence of existing antibodies against that antigen. "Furthermore, concerning the connection between allergy development and balance in Th1 versus Th2 responses, miR-29 directly targets the TBX21 mRNA (also known as T-bet), the key transcription factor of Th1 cells, and miR-181-5p targets CD4, a co-receptor of the T cell receptor expressed on Th cells." (PMID 36999032, 2023). "Therefore we investigated the effect of SNPs in the TH1 pathway (TBX21 and HLX1) on primarily TH1 and TH2 cytokine regulation early in life, a critical time window, which is relevant for early immune maturation and subsequent determination of TH2-mediated allergic diseases." (PMID 22303482, 2012).
Arthritis (2 papers, 2020 to 2021). Inflammation of a joint. "In the experimental groups that developed arthritis, Foxp3 expression correlated with Tbx21, indicating Treg polarization towards Th1." (PMID 33193352, 2020).
atopic dermatitis (2 papers, 2012 to 2021). "TBX21 encodes the Th1-specific transcription factor T-bet which is involved in Th1/Th2 balance and suppressed atopic dermatitis-like skin inflammation in mice." (PMID 34785669, 2021). "In regards to allergic outcomes assessed at age 3 years, one TBX21 polymorphism was associated with less symptoms of atopic dermatitis." (PMID 22303482, 2012). "TBX21 SNP rs11079788 carriers developed less symptoms of atopic dermatitis at 3 years of age (p = 0.03)." (PMID 22303482, 2012). "The distribution of children that developed atopic diseases within the different TBX21 and HLX1 genotypes (WT, HT and SNP) is described in the following: homozygous carriers of TBX21 rs11079788 SNP showed less symptoms of atopic dermatitis (19%) compared to HT (23%) and WT (36%) (p = 0.03)." (PMID 22303482, 2012).
B-cell chronic lymphocytic leukemia (2 papers, 2025). "Meanwhile, IFN-γ is required for the expression of T-bet (encoded by TBX21) via the JAK-STAT pathway in chronic lymphocytic leukaemia cells." (PMID 41459486, 2025).
Chagas disease (2 papers, 2016 to 2022). A parasitic infection caused by Trypanosoma cruzi. "In Chagas disease, TBX21 and IFN-γ expression are correlated with the left ventricular dilation, and the ratio between TBX21 and GATA3 expression is significantly higher in CCC than in non-inflammatory cardiomyopathy, which were also confirmed in our data in both control to CCC or DCM comparisons." (PMID 36072583, 2022).
Crohn disease (2 papers, 2015 to 2016). A gastrointestinal disorder characterized by chronic inflammation involving all layers of the intestinal wall, noncaseating granulomas affecting the intestinal wall and regional lymph nodes, and transmural fibrosis. "Tbx21 expression is implicated in the abnormal expression of IFNγ in Crohn’s disease and GATA-3 is involved in the immunopathology of ulcerative colitis." (PMID 27530627, 2016). "High levels of both TBX21 and IFNG transcripts are seen in human Crohn’s disease and TBX21 SNPs are linked with resistance to human pulmonary tuberculosis." (PMID 27530627, 2016).
gout (2 papers, 2016 to 2019). A condition characterized by painful swelling of the joints, which is caused by deposition of urate crystals. "TBX21 was 5.6-fold greater (p = 0.029) in patients with PsA than in those with OA and 25-fold greater (p = 0.0001) than in patients with gout." (PMID 27964744, 2016). "CXCL10, IL-17A, and TBX21 expression were elevated in SF cells of patients with PsA compared with those of patients with OA and gout, but not those of patients with RA." (PMID 27964744, 2016).
influenza (2 papers, 2019). An acute viral infection of the respiratory tract, occurring in isolated cases, in epidemics, or in pandemics; it is caused by serologically different strains of viruses (influenzaviruses) designated A, B, and C, has a 3-day incubation period, and usually lasts for 3 to 10 days. "The Cytotoxic/T cells/NK/Tbx21/Eomes modules (L35 and B15), were most abundant during infection with T. gondii and influenza but significantly under-abundant during B. pseudomallei infection, whereas the Ifng module, was abundant in all three infections." (PMID 31253760, 2019). "Published transcriptional profiles of NK cells, ILC1, and influenza-specific Id2-deficient mouse CD8+ T cells showed a striking concordance of Id2-dependent expression with our innateness gradient genes, highlighted by TBX21, ZEB2, IL18RAP, CCR7, TCF7, cytotoxicity, and KLR genes." (PMID 30737409, 2019).
leukemia (2 papers, 2016 to 2021). A malignant (clonal) hematologic disorder, involving hematopoietic stem cells and characterized by the presence of primitive or atypical myeloid or lymphoid cells in the bone marrow and the blood. "In addition to gene mutations that are known to be involved in leukemogenesis, such as ones in MYC and KRAS, we also identified mutations within PTPN21, TBX21, USP54, USP11, NCOR2, CSPP1 that have never before been identified in human leukemia." (PMID 26527318, 2016).
metastatic tumor (2 papers, 2020 to 2025). "Our data demonstrate that TBX21 expression was highly upregulated in malignant canine tumors in comparison to healthy tissue as well as benign and metastatic tumors." (PMID 32225066, 2020). "To examine the relationship between TBX21 expression and CRC metastasis, we performed immunohistochemistry on human CRC tissue microarrays containing 68 primary and liver metastatic tumor samples (34 primary tumor tissues and 34 liver metastatic tumor tissues)." (PMID 39744435, 2025).
schizophrenia (2 papers, 2024 to 2026). A major psychotic disorder characterized by abnormalities in the perception or expression of reality. "Within the analytic sample, schizophrenia responders (n = 6) had higher baseline TBX21 and RORC expression than non-responders (n = 8)." (PMID 42281898, 2026). "The data suggest that a TBX21/RORC-defined, Th1/Th17-skewed T-cell signature may characterize a rituximab-responsive immunopsychiatric subtype of schizophrenia, in which B-cell depletion may secondarily modulate pathogenic T-cell response." (PMID 42281898, 2026).
steatosis (2 papers, 2021 to 2022). Increased lipid within the cytoplasm of cells. "Patients with genotype TT of TBX21 gene had a statistically significantly higher steatosis grade evaluated by CAP compared to other genotypes (p = 0.009), but fibrosis stage evaluated by FIB-4 or liver stiffness did not variate according to genotype." (PMID 36330082, 2022). "Our group recently demonstrated that the allele 1993C of the SNP rs4794067 of gene TBX21 (T-box transcription factor 21), but not CYP3A5*3 genotype may predispose to the development of late significant fibrosis and severe steatosis of the liver graft." (PMID 35096933, 2021).
T-cell lymphomas (2 papers, 2020 to 2024). "FAT1 mutations spanned over the two main GATA3/TBX21 subgroups of peripheral T-cell lymphomas not otherwise specified." (PMID 31028364, 2020).
abscess (1 paper, 2022). An inflammatory process characterized by the accumulation of pus within a newly formed tissue cavity which is the result of a bacterial, fungal, or parasitic infection or the presence of a foreign body. "After infection with S. aureus, an extended level of bacteria and abscess formation in the kidney was found in mice with T-bet-deficiency in Th17 fate cells at day 10 after infection compared to T-bet/Tbx21-wildtype mice." (PMID 35446923, 2022).
actinopathy (1 paper, 2022). "Recently described IEIs associated with allergic inflammation such as T-bet deficiency caused by TBX21 variants, or the actinopathy ARPC1B deficiency, are therefore not captured in this study." (PMID 35273610, 2022).
acute coronary syndrome (1 paper, 2022). Signs and symptoms related to acute ischemia of the myocardium secondary to coronary artery disease. "A recent study found a significantly increased TBET/GATA3 mRNA ratio in patients with AMI throughout most of the first 20 h after symptom onset, which suggested that TBX21 could promote the progression of acute coronary syndrome." (PMID 35498008, 2022).
aplastic anemia (1 paper, 2020). Anemia resulting from bone marrow failure (aplastic or hypoplastic bone marrow). "In aplastic anemia patients, the promoter of TBX21 (T-bet coding gene) binds to NICD1 (the active form of Notch1) to regulate Th1-mediated immune response." (PMID 33224898, 2020).
autoimmune uveitis (1 paper, 2018). An autoimmune form of uveitis (disease). "This study shows significant DNA methylation dynamics corresponding with mRNA expression changes of Tbx21 and Rorc in the inflamed tissue of mice undergoing experimental autoimmune uveitis." (PMID 30254507, 2018). "In addition, aberrant expressions of Tbx21, Gata3, and Foxp3 have been observed in experimental autoimmune uveitis models." (PMID 30254507, 2018).
B-cell neoplasm (1 paper, 2022). A group of heterogeneous lymphoid tumors generally expressing one or more B-cell antigens or representing malignant transformations of B-lymphocytes. "The TBX21 gene encodes for T-bet protein, a T-box transcription factor expressed in B cell precursors, and involved in the oncogenesis of T-bet-positive B-cell neoplasms." (PMID 35955786, 2022).
breast tumors (1 paper, 2018). "Infiltration of >30% of breast tumors by CD8+, TBET+ T-cells (T-box transcription factor TBX21, a marker of type 1 T-cells) and more generally, Th1 type cells, can predict improved DFS, while the presence of Th2 and FoxP3+ are more generally associated with worse survival rates." (PMID 29439457, 2018).
cardiomyopathy (1 paper, 2021). A disease of the heart muscle or myocardium proper. "In response to IL-27, gene expression of TBX21, EOMES, and CXCL9, which are activated downstream of STAT1, STAT3, and STAT5 phosphorylation, was lower in patients with cardiomyopathy (i.e., the G1 and G2 groups) than that in uninfected subjects." (PMID 34061845, 2021).
cervical cancer (1 paper, 2015). A primary or metastatic malignant neoplasm involving the cervix. "Since the immune response in cervical cancer is predominantly characterized by Th1, Th2, Th17 and Treg cells, the contributions of the ‘T cells’ signature marker TBX21 and the ‘Th2’ signature marker IL5 were studied." (PMID 25889974, 2015).
Chlamydia infection (1 paper, 2022). "Since Th1 cells are defined by the expression of the master transcription factor T-bet (Tbx21), we hypothesized that IFN-γ-producing CD4 T cells responding to Chlamydia infection would express T-bet." (PMID 35196366, 2022).
Cognitive impairment (1 paper, 2022). Abnormal cognition is characterized by deficits in thinking, reasoning, or remembering. "In this study, we found reduced NK cell cytotoxicity and expansion in a unique subset of CX3CR1+TBX21+ NK cells associated with cognitive impairment in AD patients." (PMID 36405736, 2022).
deep vein thrombosis (1 paper, 2021). "Lack of Tbx21 reduces monocytic interleukin-12 formation and accelerates thrombus resolution in deep vein thrombosis." (PMID 33717169, 2021).
demyelination (1 paper, 2025). "However, Tbx21-deficient Th1 cells can promote oligodendrocyte differentiation and remyelination in a mouse model of demyelination." (PMID 40162097, 2025).
endotoxemia (1 paper, 2015). "We examined the differentiation of CD4+ lymphocytes by measuring the master genes, including the Tbx21 for Th1, the Rorc for Th17, Gata3 for Th2, and Foxp3 for Treg to evaluate whether hyperglycemia and endotoxemia synergistically modulate the balance between pro- and anti-inflammatory responses." (PMID 26207186, 2015). "In the analysis of the transcriptional factors of CD4+ T lymphocytes, the interaction between endotoxemia and hyperglycemia was not statistically significant in the effect on Tbx21 or Rorc, but was in the effect on Gata3 and Foxp3." (PMID 26207186, 2015). "There were no independent significant effects of endotoxemia or hyperglycemia on Tbx21 and Rorc mRNA." (PMID 26207186, 2015).
esophageal adenocarcinoma (1 paper, 2023). A malignant tumor with glandular differentiation arising predominantly from Barrett mucosa in the lower third of the esophagus. "Significant lower infiltration of CD8 T cells and M1 macrophages and a lower expression of CD8A, CD8B, and TBX21 were found also in Esophageal Adenocarcinoma TCGA panCancer Atlas in the normal tissue of patients with nodal metastasis." (PMID 36281585, 2023).
glioblastoma multiforme (1 paper, 2018). "We conducted expression profiling of CD274 (PD-L1), GATA3, IFNG, IL12R, IL12RB2, IL4, PDCD1 (PD-1), PDCD1LG2 (PD-L2), and TBX21 (T-bet) using data of 158 glioblastoma multiforme (GBM) patients with clinical information available at The Cancer Genome Atlas." (PMID 29721184, 2018).
inclusion body myositis (1 paper, 2025). A slowly progressive degenerative inflammatory disorder of skeletal muscles characterized by late onset weakness of specific muscles and distinctive histopathological features. "Inclusion body myositis (IBM) is an idiopathic inflammatory myopathy characterized by muscle-infiltrating KLRG1+ and TBX21+ cytotoxic T cells and type 1 inflammation." (PMID 40502583, 2025).
infectious mononucleosis (1 paper, 2022). A condition characterized by an increase in mononuclear white blood cells and swollen lymph nodes, which is usually caused by infection with the Epstein-Barr virus. "In humans, CD4+ CTLs from infectious mononucleosis patients or CMV-infected individuals have been shown to express Tbx21, Granzymes, and NKG7, as we have demonstrated." (PMID 36077655, 2022).
injury (1 paper, 2025). Damage inflicted on the body as the direct or indirect result of an external force, with or without disruption of structural continuity. "Our findings show that the Tbx21 transcription factor promotes NMJ reinnervation to regain muscle function following nerve injury." (PMID 40162097, 2025).
latent infection (1 paper, 2018). "Dexamethasone treatment suppressed the expression of tbx21 in uninfected fish (P=0.052) and in fish with a latent infection (P=0.02)." (PMID 29590635, 2018).
liver diseases (1 paper, 2023). "Significant differences in genotype distribution were observed for rs225014 (DIO2) and rs4794067 (TBX21) between groups of patients affected by different HBV-related liver diseases." (PMID 37059745, 2023).
myositis (1 paper, 2025). "In Dataset D, mDC-specific genes from all three subsets were generally more strongly correlated with markers of the IFN-II pathway, T cell markers (including TBX21 and KLRG1), and macrophages for IBM patients than other myositis and CTRL patients." (PMID 40502583, 2025).
non-small cell lung carcinoma (1 paper, 2025). A group of at least three distinct histological types of lung cancer, including non-small cell squamous cell carcinoma, adenocarcinoma, and large cell carcinoma. "A prospective study involving 89 early-stage non-small cell lung cancer patients demonstrated that SBRT increased CD4+ and CD8+ T-cell levels and significantly changed transcription factors such as TBX21, GATA-3, and FOXP3." (PMID 40283008, 2025).
prostate carcinoma (1 paper, 2025). A carcinoma that arises from epithelial cells of the prostate gland. "TBX21 expression was markedly elevated in prostate cancer cell lines compared with RWPE-1, with the highest levels observed in AR-positive cells." (PMID 41573646, 2025).
sarcoma (1 paper, 2022). A usually aggressive malignant neoplasm of the soft tissue or bone. "Furthermore, we reveal five targetable antigens (C16orf54, CCR8, CYTIP, SAMD3 and TBX21) by identifying modules associated with the sarcoma immune landscape." (PMID 36153483, 2022). "Furthermore, this study identified specific molecules (C16orf54, CCR8, CYTIP, SAMD3 and TBX21) that can be used as predictors of the risk of progression and therapeutic targets for patients with sarcomas." (PMID 36153483, 2022).
Splenomegaly (1 paper, 2020). Abnormal increased size of the spleen. "Upon gross examination it was apparent, that Tbx21+/+ wild type mice developed a massive splenomegaly, which was strongly curtailed in either Tbx21 deficient strain (Tbx21-/- and Tbx21E/E)." (PMID 32991634, 2020).
spondyloarthritis (1 paper, 2017). "NK and CD8 T-cells expressing T-bet are increased in AS cases, risk variants of TBX21 lead to increased expression in AS cases, and TBX21 knockout mouse are resistant to the development of spondyloarthritis and IBD in the Skg mouse model." (PMID 29333268, 2017).